SLC7A11 (solute carrier family 7 member 11)
Diseases named in the same sentence as SLC7A11 in open-access papers (continued):
Sharing a sentence is not in itself a finding about the gene and the disease.
osteosarcoma (continued). "In conclusion, we reveal that p62 play an important role for SLC7A11 autophagic degradation and our data suggest that SFN exerts its anti-osteosarcoma effects by inducing ferroptosis through targeting p62, leading to the degradation of SLC7A11 via the lysosomal pathway." (PMID 39657365, 2024). "Targeting SLC7A11 in vivo has been shown to impede tumor growth in osteosarcoma." (PMID 37892851, 2023). "In addition, under hypoxia conditions, the prodrug tirapazamine was reported to decrease proliferation and induce ferroptosis in osteosarcoma 143B and U2OS cells; the biological functions were linked to the inhibition of SLC7A11 and GPX4." (PMID 36819098, 2023). "Osteosarcoma cell lines also exhibited elevated expression of SLC7A11." (PMID 37460542, 2023). "Taken together, this study reveals a novel mechanism in which super-enhancer-driven MLX positively regulates SLC7A11 to meet the alleviated demand for cystine and maintain the redox balance, highlighting the feasibility and clinical promise of targeting SLC7A11 in osteosarcoma." (PMID 37460542, 2023). "In addition, KDM4A, a histone demethylase with the function of demethylating H3K9me3 in the promoter region of SLC7A11, inhibited ferroptosis-related cell death in osteosarcoma." (PMID 36819098, 2023). "KDM4A-regulated SLC7A11 decreases ferroptosis of osteosarcoma cells." (PMID 34177591, 2021). "Under hypoxic conditions, SLC7A11 expression is reduced, whereas increases in MDA and Fe2+ levels increase ROS accumulation in osteosarcoma cells." (PMID 40740786, 2025). "For example, telaprevir downregulates SLC7A11 and GPX4 expression, thereby inducing ferroptosis in osteosarcoma cells." (PMID 39812923, 2025). "What's more, the tirapazamine (TPZ) can also downregulate the expression level of SLC7A11 and GPX4 and increase the level of MDA and Fe2+ which can lead to osteosarcoma cell produce more ROS inducing ferroptosis." (PMID 38800967, 2024). "Mechanistically, MLX regulates the glutamate/cystine antiporter SLC7A11 to promote the uptake of extracellular cystine for biosynthesis of the essential antioxidant GSH, thereby maintain the redox balance in osteosarcoma cells." (PMID 37460542, 2023).
osteosarcoma (continued). "Additionally, butyrate (HDAC inhibitor) inhibits SLC7A11 transcription by upregulating ATF3 expression and promoting ferroptosis in osteosarcoma cells, thus alleviating osteosarcoma." (PMID 40846688, 2025). "Mechanistically, MLX regulates the glutamate/cystine antiporter SLC7A11 to promote extracellular cysteine uptake required for the biosynthesis of the essential antioxidant GSH, thereby detoxifying reactive oxygen species (ROS) and maintaining the redox balance of osteosarcoma cells." (PMID 37460542, 2023).
bladder cancer (38 papers, 2015 to 2026). "Different from SLC7A11 in bladder carcinoma, the high expression of AIFM2 was significantly associated with the good OS and RFS." (PMID 34722530, 2021). "Recent research has reported that USP52 inhibition promoted ferroptosis by inhibiting SLC7A11/xCT in bladder cancer." (PMID 40962058, 2025). "The latest research has revealed that USP52 promoted bladder cancer progression by modulating ferroptosis through stabilizing SLC7A11/xCT." (PMID 40962058, 2025). "PCBP2 stabilizes the mRNA of the ferroptosis inhibitor SLC7A11, which inhibits ferroptosis in tumors and accelerates bladder cancer progression." (PMID 39816681, 2025). "For instance, miR‐204/CD44 axis, miR‐1247‐3p/FOXO1 axis, and miR‐26a‐5p/SLC7A11 axis have been implicated in NSCLC, bladder cancer, and OSCC, respectively." (PMID 39177014, 2024). "Recent studies have shown that the solute transporter family member SLC7A11 is not only a key component of the cystine/glutamate antiporter (XC system) but also an important regulator of bladder cancer resistance to cisplatin." (PMID 36936418, 2023). "Studies have shown that high expression of SLC7A11 is closely related to cisplatin resistance in bladder cancer." (PMID 37152941, 2023). "Alterations in miR-27a levels are involved in cisplatin resistance in bladder cancer through modulating the expression of the SLC7A11 and intracellular GSH." (PMID 36876051, 2023). "Overexpression of miR-27A significantly decreases SLC7A11 expression and enhances sensitivity to bladder cancer cells toward cisplatin." (PMID 36685879, 2022). "miR-27A is downregulated in bladder cancer tissue samples and is involved in enhancing cisplatin resistance by regulating the expression of Solute Carrier Family 7 Member 11 (SLC7A11)." (PMID 36685879, 2022). "Evidence has shown that crucial regulatory proteins in ferroptosis such as GPX4 and SLC7A11 also function as important triggers in the regulation of tumor-related signaling mechanisms such as tumorigenesis of bladder cancer." (PMID 34728613, 2021). "Drayton and colleagues found that miR-27a suppresses protein expression of cystine/glutamate transporter SLC7A11 in cisplatin-resistant bladder cancer." (PMID 27834829, 2016). "Elevated levels of SLC7A11 are considered to be an unfavorable prognostic indicator for Overall Survival (OS) in 8 distinct forms of cancer, including adrenocortical carcinoma, PC, bladder cancer, and head and neck squamous cell carcinoma." (PMID 38994627, 2024). "Notably, a certain dose of sulfasalazine can eliminate the cisplatin resistance of SLC7A11-induced bladder cancer." (PMID 36936418, 2023). "Cisplatin-resistant bladder cancer cell lines were resensitized by initiating miR-27a expression, or reducing the activity of SLC7A11 via siRNA, which supports the findings that miRNAs can regulate cellular transporters, thus connoting regulation of cellular chemoresistance." (PMID 28918032, 2017). "Bladder cancer with low miR-27a or high SLC7A11 expression exhibited poorer clinical outcomes." (PMID 27834829, 2016). "In addition, SLC7A11 was inversely correlated with clinical outcome in bladder cancer and negatively regulated by a microRNA for cisplatin-resistant cells." (PMID 25622337, 2015). "FADS2 regulates ferroptosis in bladder cancer by influencing the expression of GPX4 and SLC7A11, but the upstream regulators of FADS2 remain to be explored." (PMID 40682485, 2025).
bladder cancer (continued). "In this study, we observed elevated expression levels of TMBIM6 and ferroptosis-related proteins (GPX4, SLC7A11, and FTH1) in bladder cancer tissues, while CAM expression was significantly downregulated." (PMID 40610429, 2025). "In TGF-β1-induced mesenchymal-like bladder cancer cells, ferroptosis-related genes (GPX4, SLC7A11) were markedly elevated, alongside increased lipid peroxides (LPO) and glutathione (GSH) levels." (PMID 41413023, 2025). "Building upon these previous findings, our study has made a novel observation in bladder cancer: we identified significantly elevated expression levels of TMBIM6 and ferroptosis-related proteins (GPX4, SLC7A11, and FTH1) in clinical bladder cancer specimens." (PMID 40610429, 2025). "TMBIM6, ferroptosis-related proteins (GPX4, SLC7A11, and FTH1), and calmodulin (CaM) expressions in bladder cancer and paracancerous tissues were obtained by immunohistochemistry." (PMID 40610429, 2025). "In bladder cancer cells, erianin evoked ferroptosis by inducing NRF2 inactivation characterized by decreased FTH1, GPX4, HO-1, and xCT/SLC7A11 expression as well as the accumulation of ROS and the depletion of GSH." (PMID 39021832, 2024). "Our study has identified four disulfidptosis suppressor genes, namely SLC7A11, SLC3A2, RPN1, and NCKAP1, which play significant roles in the development and immune infiltration of bladder cancer." (PMID 37152941, 2023). "OTUB1 expression is markedly elevated in human bladder cancers; knockdown of OTUB1 expression diminishes endogenous SLC7A11, which subsequently enhances ROS-mediated ferroptosis in bladder cancer cell lines." (PMID 36505448, 2022). "MiRNA-27a down-regulation can targetedly promote SLC7A11 and regulate GSH biosynthesis, thus enhancing the resistance of bladder cancer cells to cisplatin in vitro." (PMID 34869390, 2021). "Recent studies have reported xCT (SLC7A11), in particular, as a drug resistance maker and a novel target for therapeutic interventions in lung, breast, head & neck, and bladder cancers." (PMID 27144525, 2016). "In contrast to our previous findings, TalaA-triggered ferroptosis of bladder cancer cells does not occur through the inhibition of SLC7A11 expression but rather through the upregulation of transferrin and heme oxygenase 1 in bladder cancer cells." (PMID 37866481, 2023). "For example, Liu demonstrated that SLC7A11 could be regulated by OTUB1 in cancer cells and facilitate ferroptosis resistance in bladder cancer using T24 Cell and UM-UC 3 Cell as experimental models." (PMID 34728613, 2021). "In order to correlate xCT expression and methylation, we determined the SLC7A11 (xCT) methylation status in bladder cancer patients (n = 52) and their matched non-tumor tissues (n = 106) and found significant hypomethylation of SLC7A11 in tumors compared to their matched non-tumor tissues." (PMID 27823983, 2016).
cervical cancer (34 papers, 2021 to 2026). A primary or metastatic malignant neoplasm involving the cervix. "The results demonstrate that Gboxin significantly decreased the mRNA levels of GPX4, FSP1, and SLC7A11 in cervical cancer cells cultured under low-glucose conditions." (PMID 39859216, 2025). "SLC7A11 promotes cervical cancer cell survival by mediating cystine uptake to maintain glutathione synthesis, thereby inhibiting ferroptosis." (PMID 40895556, 2025). "The RACK1/miR-1275/FUT8 axis stabilizes SLC7A11 through core-fucosylation, preventing its degradation and thus inhibiting ferroptosis, which promotes cervical cancer cell survival and progression." (PMID 40895556, 2025). "Under hypoxia-like conditions, cervical cancer cells increase SLC7A11 expression through KDM4A SUMOylation at the K471 site, which reduces H3K9me3-mediated repression of SLC7A11, thereby enhancing GPX4 levels and promoting ferroptosis resistance." (PMID 40895556, 2025). "Mechanically, SNG induces H2O2-dependent cell ferroptosis in human cervical cancer (HeLa) cells by downregulating SLC7A11 and glutathione." (PMID 40630130, 2025). "SLC7A11 plays a critical role in suppressing ferroptosis in cervical cancer by mediating cystine uptake for glutathione synthesis." (PMID 40895556, 2025). "SLC7A11, functioning as a cystine/glutamate antiporter, shows that its high expression is significantly correlated with shortened overall survival in cervical cancer patients." (PMID 41479924, 2025). "E6 and E7 can exacerbate glutaminolysis in cervical cancer cells, although only E7 can increase SLC7A11 gene expression, thereby increasing the malignant phenotype." (PMID 39769017, 2024). "circEPSTI1, which is highly expressed in cervical cancer, inhibits ferroptosis, which downregulates miR-409-3p and miR-515-5p and upregulates SLC7A11, suggesting miR-409-3p and miR-515-5p are ferroptosis-inducing miRNAs." (PMID 38892270, 2024). "As a competing endogenous RNA (ceRNA), circEPSTI1 upregulates the expression of SLC7A11 by adsorbing miR-375, miR-409-3p, and miR-515-5p in cervical cancer cells." (PMID 37332354, 2023). "Silencing of circEPSTI1 inhibited cervical cancer cell proliferation and induced SLC7A11-mediated ferroptosis, and overexpression of SLC7A11 reversed this effect." (PMID 37332354, 2023). "On one hand, propofol and paclitaxel can activate the apoptosis pathway in cervical cancer cells; on the other hand, their combination can also induce ferroptosis by regulating the SLC7A11/GPX4 pathway." (PMID 37891669, 2023). "Various ferroptosis-associated traditional signals such as SLC7A11, GPX4, and ACSL4 have been uncovered in cervical cancer, and it seems that circRNAs provide prominence to regulate ferroptosis-related signals in cervical cancer." (PMID 37065473, 2023). "They demonstrated that circEPSTI1 promotes cervical cancer cell proliferation by regulating SLC7A11-mediated ferroptosis." (PMID 35321435, 2022). "For example, miR-375-3p can promote ferroptosis of cervical cancer cells by targeting SLC7A11, and can be used as a potential gene therapy drug." (PMID 36408273, 2022). "Up-regulated circRNA circEPSTI1 promotes cervical cancer growth by negatively regulating SLC7A11-dependent ferroptosis." (PMID 35321435, 2022). "circEPSTI1 modulates the proliferation of cervical cancer via the miR-375/409-3P/515-5p-SLC7A11 axis relative to ferroptosis." (PMID 35652072, 2022). "SLC7A11, a cystine/glutamate antiporter, not only enhances cervical cancer progression by circEPSTI1-miR-375-SLC7A11 axis but also serves as an unfavorable prognostic biomarker in renal carcinoma." (PMID 35419359, 2022). "Further analysis showed that knockdown of circEPSTI1 induced ferroptosis by downregulating SLC7A11 through the mechanism of ceRNA in cervical cancer." (PMID 33534779, 2021). "We found that circEPSTI1-miR-375/409-3P/515-5p-SLC7A11 axis promotes the cervical cancer cell proliferation through a mechanism involving ceRNA." (PMID 33534779, 2021).
cervical cancer (continued). "Conclusions: circEPSTI1-miR-375/409-3P/515-5p-SLC7A11 axis affected the proliferation of cervical cancer via the competing endogenous RNAs (ceRNA) mechanism and was relative to ferroptosis." (PMID 33534779, 2021). "Targeting SLC7A11 with specific inhibitors disrupts redox balance, increases ROS, and induces ferroptotic cell death, representing a promising therapeutic strategy for cervical cancer." (PMID 40895556, 2025). "Moreover, other natural benzophenanthridine alkaloids, such as sanguinarine, also induce ferroptosis in cervical cancer cells by downregulating SLC7A11." (PMID 38892270, 2024). "CircEPSTI1 promotes cells progression by miR-375/409-3P/515-5p-SLC7A11 axis in cervical cancer." (PMID 39170701, 2024). "Therefore, inhibiting the SLC7A11/xCT axis has become a potential therapeutic strategy for cervical cancer." (PMID 39125853, 2024). "Circular RNA circEPSTI1 represses the development of cervical cancer by targeting SLC7A11." (PMID 34177591, 2021). "Silencing CNIH4 or SLC7A11 restores ferroptotic sensitivity, identifying CNIH4 as a potential prognostic biomarker and therapeutic target in cervical cancer." (PMID 40895556, 2025). "The downregulation of Fatty acid synthase promotes ferroptosis, mainly by decreasing SLC7A11 in cervical cancer, and targeting FASN enhances cisplatin sensitivity in cervical cancer." (PMID 40438588, 2025). "Among them, Solute Carrier Family 7 Member 11 (SLC7A11/xCT) is crucial for maintaining the synthesis of glutathione and the antioxidant system in cervical cancer cells." (PMID 39125853, 2024). "In addition, in cervical cancer, fatty acid synthase (FASN) promotes cisplatin resistance by upregulating SLC7A11, which suppresses ferroptosis." (PMID 40895556, 2025). "ROS, especially H2O2, reduce SLC7A11 and GPX4 expression in cervical cancer and prostate cancer; additionally, ROS stimulate BTB domain and CNC homolog 1 (BACH1) degradation by decreasing the expression of ubiquitin carboxyl-terminal hydrolase 47 (USP47), which can deubiquitinate BACH1." (PMID 39584140, 2024). "In addition, it was demonstrated that SLC7A11 was a downstream target of miR-152-3p and was activated in PCa tissue, showing the same trend in NSCLC, cervical cancer, and thyroid papillary carcinoma." (PMID 35123415, 2022). "For example, Peng Wu 85 showed that circEPSTI1 promoted the proliferation of cervical cancer via miR-375/409-3P/515-5p acting as a ceRNA by targeting SLC7A11 and attenuated the effect of lipid peroxidation and GSH/GSSG to inhibit ferroptosis of cervical cancer cells." (PMID 35342359, 2022). "In addition, Cornichon family AMPA receptor auxiliary protein 4 (CNIH4) is upregulated in cervical cancer, CHIH4 promotes tumor progression by inhibiting ferroptosis by enhancing SLC7A11-mediated cystine import, boosting glutathione synthesis and GPX4 activity." (PMID 40895556, 2025).